RNU6-1227P (RNA, U6 small nuclear 1227, pseudogene)
Gene: Small nuclear RNA gene on chromosome 3 (39,025,987 to 39,026,093, forward strand). Ensembl gene ENSG00000206708.
Homologues: Orthologues: chimpanzee U6 (100% identical), macaque U6 (94% identical), pig U6 (87% identical), rat U6 (85% identical), guinea pig U6 (82% identical), mouse Gm25797 (82% identical), rabbit U6 (79% identical). Paralogues in human: RNU6-46P (92% identical), RNU6-33P (90% identical), RNU6-38P (90% identical), RNU6-698P (90% identical), RNU6-891P (90% identical), RNU6-1 (89% identical), RNU6-116P (89% identical), RNU6-1316P (89% identical), RNU6-2 (89% identical), RNU6-22P (89% identical), RNU6-338P (89% identical), RNU6-39P (89% identical), and 1286 more.